WFDC12 (WAP four-disulfide core domain 12)
Description:
Antibacterial protein. Putative acid-stable proteinase inhibitor.
Synonyms: C20orf122; WAP2; dJ211D12.4; SWAM2
Tractability: Antibody: UniProt places it where antibodies can reach, with high confidence; UniProt predicts a signal peptide or a membrane-spanning region; its Gene Ontology location is reachable by antibodies, with medium confidence.
Gene: Protein-coding gene on chromosome 20 (45,123,425 to 45,124,465, reverse strand). Ensembl gene ENSG00000168703.
Subcellular location: Secreted
Gene Ontology:
Molecular function: protein binding; serine-type endopeptidase inhibitor activity; peptidase inhibitor activity
Biological process: antibacterial humoral response; defense response to bacterium; innate immune response
Cellular component: extracellular region
Genetic constraint (gnomAD): Loss-of-function variants: 4 observed, 8.25 expected, observed/expected ratio (o/e) 0.48, 90% interval 0.24 to 1.11. That is too few expected variants to judge how well the gene tolerates losing a copy. Missense variants: 156 observed, 141.41 expected, observed/expected ratio (o/e) 1.1, 90% interval 0.97 to 1.26. Synonymous variants: 48 observed, 52.56 expected, observed/expected ratio (o/e) 0.91, 90% interval 0.72 to 1.16.
Homologues: Orthologues: chimpanzee WFDC12 (98% identical), macaque WFDC12 (92% identical), rat Wfdc12 (40% identical), mouse Wfdc12 (37% identical), Drosophila melanogaster CG5639 (28% identical), Caenorhabditis elegans C08G9.2 (21% identical). Paralogues in human: PI3 (27% identical), SLPI (26% identical), WFDC3 (25% identical), WFDC5 (22% identical), WFDC13 (15% identical), WFDC10A (14% identical), WFDC10B (14% identical), WFDC9 (12% identical), WFDC11 (10% identical).
Diseases named in the same sentence as WFDC12 in open-access papers:
WFDC12 is named in the same sentence as 11 diseases in open-access papers, as found by Europe PMC text mining. Sharing a sentence is not in itself a finding about the gene and the disease. The quoted sentences say what the papers report.
psoriasis (2 papers, 2022 to 2024). An autoimmune condition characterized by red, well-delineated plaques with silvery scales that are usually on the extensor surfaces and scalp. "Further research is needed to better understand the precise mechanisms of these WFDC proteins and to assess the potential for WFDC12 as a therapeutic target in psoriasis." (PMID 39296934, 2024). "In psoriasis patients, WFDC12 expression increases in skin lesions and correlates with the severity of pathological features." (PMID 39296934, 2024). "WFDC12, due to its significant involvement in the progression of psoriasis, holds potential as a target for targeted therapies." (PMID 39296934, 2024). "We collected clinical skin samples (taken from the West China Hospital) and used immunohistochemical staining to detect the expression of WFDC12 protein in the skin of healthy persons and lesions area of psoriasis patients." (PMID 36148224, 2022). "The expression of WFDC12 protein in the psoriasis-like lesions area of ​​WT mice was increased in vivo." (PMID 36148224, 2022). "Several genes including WFDC12 in the WFDC family were located on human chromosome 20q13, which was in the hot spots of psoriasis susceptibility genes." (PMID 36148224, 2022). "Our study provided a strong evidence for the regulation mechanism of WFDC12 in psoriasis developing, which would be conducive to treatment of psoriasis." (PMID 36148224, 2022). "WFDC12 is considered to have a potential effect on the pathogenesis of psoriasis." (PMID 39296934, 2024). "Moreover, the mRNA level of WFDC12 was higher in the lesions of psoriasis patients relative to healthy skin tissues." (PMID 36148224, 2022). "To further explore the clinical relevance of the WFDC12 and psoriasis disease, we analyzed the clinical database and found that the expression of WFDC12 was increased with the aggravation of the pathological characteristics of psoriasis." (PMID 36148224, 2022). "Therefore, the role of WFDC12 in psoriasis initially explored the correlation between the severity of psoriasis and the expression of WFDC12." (PMID 36148224, 2022). "In this study, we found the expression of WFDC12 protein closely correlated with psoriasis." (PMID 36148224, 2022). "During the pathogenesis of psoriasis, the activation of AP-1 transcriptional regulatory factors may lead to the upregulation of WFDC12 molecule expression." (PMID 36148224, 2022). "WFDC12 was located at the susceptible site of psoriasis, specific high expression in the KCs; the role and mechanism on the pathogenesis of psoriasis had not yet been reported." (PMID 36148224, 2022). "Whey acidic protein four-disulfide core domain protein 12 (WFDC12) has been implicated in the pathogenesis of psoriasis but the specific molecular mechanism is not clearly defined." (PMID 36148224, 2022). "In the next step, we will use Th1 cytokine blockers or retinoic acid signal pathway modulators to observe whether the severity of psoriatic lesions in mice is improved after treatment, so as to further clarify the role of WFDC12 in the pathogenesis of psoriasis." (PMID 36148224, 2022). "Among the WFDC family, the high expression of WFDC4, WFDC12, and WFDC14 have been noted in the lesions of psoriasis." (PMID 39296934, 2024). "We speculate that the WFDC12 may regulate the immune system by impacting the infiltration of LCs and moDDC cells in mice after the IMQ-induced psoriasis model." (PMID 36148224, 2022). "The expression of WFDC12 was significantly increased in the lesions of psoriasis patients compared with non-lesions and healthy skin tissues." (PMID 36148224, 2022). "To identify the differential expression of WFDC12 in psoriasis patients (lesional and non-lesional) and healthy persons, we obtained the publicly available microarray datasets GDS4602, GDS5420, and GDS4600 from the GEO (Gene Expression Omnibus, National Institutes of Health)." (PMID 36148224, 2022).
psoriasis (continued). "WFDC12 may affect the certain signaling pathway to protease inhibition and lead to aggravation of inflammation in the psoriasis immune microenvironment, which has not been reported yet." (PMID 36148224, 2022). "The candidate molecule WFDC12 belongs to the WFDC protein family, with protease inhibitory function, also suggested that WFDC12 may be likely to play an important role in the “skin involved” autoimmune disease psoriasis." (PMID 36148224, 2022). "In conclusion, WFDC12 might affect the activation of the retinoic acid signaling pathway and regulate the infiltration of DC cells in the skin lesions and lymph nodes, thereby inducing Th1 cells differentiation and increasing the secretion of IFN-γ to exacerbate psoriasis in mice." (PMID 36148224, 2022).
atopic dermatitis (1 paper, 2023). "Collectively, our data demonstrate that WFDC12 may contribute to the exacerbation of AD-like symptoms in DNFB-induced mouse model by enhancing arachidonic acid metabolism and PAF accumulation and that WFDC12 may be a potential therapeutic target for human atopic dermatitis." (PMID 36882395, 2023).
cyst (1 paper, 2022). A sac-like closed membranous structure that may be empty or contain fluid or amorphous material. "WFDC12 is an anti-bacterial protein and a putative serine peptidase inhibitor, and it is also up-regulated only during cyst interactions." (PMID 35573800, 2022).
epididymitis (1 paper, 2024). Inflammation of the epididymis. "WFDC12 has been demonstrated to play an immunomodulatory and anti-inflammatory role through the inhibition of neutrophil elastase, and is upregulated in lesional psoriatic skin, wounds, scars, epididymitis in mice, and human intestinal epithelial cells under Giardia infections." (PMID 39144720, 2024).
Hypertension (1 paper, 2018). The presence of chronic increased pressure in the systemic arterial system. "The mechanism of FAM110A, PREP, ANKRD9, DCPS, WFDC12, TPTE, and LAMB2 genes on the occurrence and development of hypertension is not yet clear." (PMID 29379041, 2018).
skin (2 papers, 2022 to 2023). "Then, we examined WFDC12 protein expression level and distribution in the healthy human skin tissue and the skin lesions of AD patients by using immunohistochemical staining." (PMID 36882395, 2023).
cancer (1 paper, 2024). A tumor composed of atypical neoplastic, often pleomorphic cells that invade other tissues. "WFDC2 is commonly upregulated in multiple cancer types and inflammatory diseases and WFDC12 is upregulated in some inflammatory diseases, suggesting their utility as a diagnostic and prognostic marker." (PMID 39296934, 2024). "WFDC proteins have been found to be upregulated in many diseases, such as WFDC1, WFDC2, WFDC12, WFDC14 are upregulated in cancers, inflammatory diseases and so on." (PMID 39296934, 2024).
WFDC12 also shares sentences with these, for which no sentence is quoted: autoimmune disease (1 paper); Erythema (1); Giardia infections (1); ichthyosis (1).